NRP1 (neuropilin 1)
Diseases named in the same sentence as NRP1 in open-access papers (continued):
Sharing a sentence is not in itself a finding about the gene and the disease.
cancer (continued). "However, more research is required to understand how NRP1’s molecular mechanism contributes to the development and spread of cancer." (PMID 40277760, 2025). "Despite the promise of targeting NRP1 in cancer therapy, several challenges remain." (PMID 40277760, 2025). "Additionally, neuropilin-1 (NRP1), a membrane-bound glycoprotein, has emerged as a critical mediator of cancer progression and chemoresistance." (PMID 40314246, 2025). "Metabolomic studies have begun exploring how NRP1 influences cellular metabolism in cancer." (PMID 40277760, 2025). "This review highlights the pivotal role of NRP1 in cancer pathogenesis and discusses its implications for developing targeted therapeutic approaches to improve patient outcomes, highlighting the role of OMICS in targeting cancer patients for personalized therapy." (PMID 40277760, 2025). "Research continues to focus on better understanding the complex roles of VEGF and NRP1 in cancer." (PMID 40277760, 2025). "Additionally, the complexity of NRP1 signaling and its interactions with multiple ligands necessitate further research to elucidate its role in different cancer types and stages fully." (PMID 40277760, 2025). "A growing body of research shows that NRP1 is a distinct immune modulator in cancer immunotherapy." (PMID 40277760, 2025). "In our case, when more stable and active inhibitors are developed, we then plan to use them as targeting vector (molecule) in radioconjugates, that can be used as theranostic-like radiopharmaceuticals for the imaging and therapy of cancers that overexpress NRP-1." (PMID 39181965, 2024). "While NRP-1 has been extensively studied in mice and to a lesser extent in humans, particularly in the context of neuronal guidance, cancer, and other diseases, the role of its soluble form (sNRP-1) as an antagonist of NRP-1 remains unclear." (PMID 38791476, 2024). "Compounds that block this interaction are potential inhibitors of the VEGF-A165/NRP-1 complex that may find application in the diagnosis and therapy of cancer." (PMID 39181965, 2024). "Additionally, NPR1’s role as a co-receptor for TGF-β1 facilitates cell proliferation and metastasis, further implicating NRP1 in cancer development and spread." (PMID 39334861, 2024). "In the context of cancer, NRP1 inhibitors would be expected to suppress NGF-evoked pain and VEGF-A–mediated angiogenesis in tumors, although impaired wound healing could be a liability." (PMID 39589827, 2024). "NRP1 and NRP2 have already been implicated in cancer invasion, metastasis and progression, but this is not the case for SEMA3F, which has been traditionally considered a good prognostic marker not only for BC but also for several other types of cancer." (PMID 39138514, 2024). "TAM-derived VEGFA may promote cancer stemness of TNBC through the NRP-1/GAPVD1/Wnt/β-catenin axis in an autocrine and paracrine manner." (PMID 38169627, 2024). "NRP1 can also promote resistance to molecularly targeted therapies in cancer." (PMID 37894289, 2023). "Experimental inhibition of NRP1 activity can display antitumor effects in different cancer models." (PMID 37894289, 2023). "In addition, H3K4me3 enrichment was also decreased at the promoters of Myc, WW domain-containing transcription regulator protein 1 (Wwtr1) and neuropilin 1 (Nrp1), which participate in cancer metastasis, after GATM knockdown." (PMID 37370109, 2023). "NRP-1 has been documented in neurons, T-cells, dendritic cells and migrating cancer cells." (PMID 37138283, 2023). "However, NRP1 expression regulation via CD in cancers and the potential roles and mechanisms of SARS-CoV-2 infection are not clear." (PMID 38138098, 2023). "Cancer cell lines treated with CD, an adenosine derivative, downregulated the NRP1 expression." (PMID 38138098, 2023). "However, NRP1 expression in pan-cancers, its regulation, and the potential role of SARS-CoV-2-infected cancer patients are not clear." (PMID 38138098, 2023).
cancer (continued). "Due to the important role of neuropilin-1 in immune processes, cancer and neurodegenerative disorders, the developed method may serve as a tool to study its role as a potential biomarker of diseases." (PMID 37112459, 2023). "Recently, increasing evidence suggested that NRP1 plays a critical role in various cancers." (PMID 36841806, 2023). "In this study, we analyzed the NRP1 expressions and viral syncytial formation in cancer cell lines." (PMID 38138098, 2023). "Furthermore, tuftsin binds to the transmembrane receptor neuropilin-1 (Nrp1), which is known to play critical roles in immunity and in cancer development." (PMID 37895899, 2023). "Likewise, HIF-1α also modulated epithelial-to-mesenchymal transition (EMT) through the VEGFA/NRP1 axis in low Gleason grade cancers." (PMID 36376373, 2023). "Considering these findings and the close association of NRP1 and lenvatinib with cell migration and angiogenesis in cancer, we performed the next experiments in the Hep3B and Huh-7 cell lines to precisely evaluate the role of NRP1 in lenvatinib efficacy in HCC." (PMID 36376373, 2023). "Indeed, we found that the interaction between PRV and EGFR depends on NRP1, as it mediates virus entry into cancer cells via macropinocytosis and lipid raft-dependent endocytosis." (PMID 37891570, 2023). "However, NRP1 expression regulation by CD in cancers, and the potential role and mechanism of SARS-CoV-2 infection are not clear." (PMID 38138098, 2023). "A recent review outlines the various functions of NRP1 in the context of cancer treatments." (PMID 37513474, 2023). "Combined with our finding that SNAI2 was strongly related to the expression of CD276, NRP1, and CD44 in many cancer types, we speculated that the potential association between SNAI2 and CD276, CD44, or NRP1 was promising for our further studies." (PMID 37251370, 2023). "NRP1 expression is upregulated in many cancer types, including kidney renal clear cell carcinoma (KIRC) and kidney renal papillary cell carcinoma (KIRP), compared to the matched healthy tissues and is positively correlated with the survivability rate of KIRC patients." (PMID 38138098, 2023). "Therefore, NRP1 can be a checkpoint target with significant implications for cancer immunology and immunotherapy." (PMID 36841806, 2023). "Research by Dario A.A. Vignali’s team suggests that blocking NRP1, a potential immune checkpoint in T cells, could improve immunotherapy and help prevent cancer recurrence." (PMID 36923439, 2023). "Both CD96 and NRP1 prevented cancer cells against the immune system, blocked them and could improve immunotherapy and help prevent cancer recurrence." (PMID 36144737, 2022). "Here, we review the structural requirements for the interactions of CgA and CgA-fragments with neuropilin-1 and integrins, their biological effects, their mechanisms, and the potential use of compounds targeting these ligand-receptor interactions for cancer diagnosis and therapy." (PMID 36559048, 2022). "Pan-cancer analysis revealed that the isoform NRP1-202 might be involved in both tumorigenesis and SARS-CoV-2 infection processes." (PMID 36338984, 2022). "This research is among the first to consider the effect of hit compounds on multiple diseases, which represents a vital step toward developing small-molecule inhibitors of the VEGF-A/NRP1 signalling for the treatment of neuropathic pain, cancer, and potentially also of SARS-CoV-2 infections." (PMID 35955539, 2022). "Besides, there was a robust positive relationship between PDIA3 and CD276 and Neuropilin-1(NRP1) in most of the TCGA cancers." (PMID 35401558, 2022). "However, in most cancer types, NRP1 functioned as a potential oncogene, which was consistent with previous studies." (PMID 36338984, 2022). "The mechanisms modulating NRP1 expression in cancer cells are controversial." (PMID 35993027, 2022).
cancer (continued). "Therefore, it is critical to predict the susceptibility to SARS-CoV-2 and prognosis after infection among healthy people and cancer patients based on expression of NRP1." (PMID 36338984, 2022). "Next, we estimated the expression profiles of NRP1 across pan-cancers." (PMID 36338984, 2022). "Nonetheless, despite the biological and clinical evidence supporting the critical role of NRP1 in cancer, there is a lack of studies that assess the potential association between NRP1 overexpression and clinical outcomes in cancer." (PMID 35884516, 2022). "Neuropilin-1 (NRP-1) is a surface receptor found on many types of cancer cells." (PMID 35056995, 2022). "The mRNA expression of NRP1 in different cancer types compared with normal tissues." (PMID 36338984, 2022). "Other compounds that can antagonize NRP-1 have shown promise in preclinical cancer studies." (PMID 36557705, 2022). "We next did a pan-cancer analysis between NRP1 (ENSG00000099250.17) and OS of patients with GEPIA2." (PMID 36338984, 2022). "denoting a correlation of Nrp1 expression with cancer stemness." (PMID 36203599, 2022). "In addition, NRP-1 positively regulates the immune response to cancer cells and malignant tumors through the regulation of CD8+ infiltration into solid tumors." (PMID 36009579, 2022). "The overexpression of NRP-1 indicates that it plays a vital role in cancer progression." (PMID 34868634, 2021). "Interestingly, we also observed upregulations of genes involved in axonal guidance—L1 cell adhesion molecule (L1CAM), neuropilin-1, semaphorins, and ephrins, indicating potential interactions of cancer cells and neuronal components of the stroma." (PMID 35008571, 2021). "LINC02672 was significantly correlated with the expression of IDO1, NRP1 and TNFSF4 in pan‐cancers, and it was significantly associated with the abundance of CD56 bright natural killer cells, mast cells, and immature dendritic cells in pan‐cancers." (PMID 33797188, 2021). "Therefore, VEGF and its receptors (VEGFR1 and VEGFR2, and NRP1) are targeted for treating cancer and vascular diseases." (PMID 34698182, 2021). "Interestingly, we also observed upregulations of genes involved in axonal guidance like L1CAM, NRP1, semaphorins, and ephrins, emphasizing potential interactions of cancer cells and neuronal components of the stroma." (PMID 35008571, 2021). "A number of NRP1-targeting strategies have been developed to treat cancer." (PMID 34961486, 2021). "NRP-1 has been shown to play a role in promoting the migration of cells from other cancer types." (PMID 33912463, 2021). "NRP1 is overexpressed in many cancers but naturally upregulated in lung and heart tissue." (PMID 34401749, 2021). "However, since the role of NRP1 in pathological vascular permeability has been mainly studied in preclinical models of neovascular eye diseases and cancer, we will now focus on NRP1 regulation of vascular permeability in these two sets of diseases." (PMID 33947161, 2021). "It would be reasonable to believe that targeting NRP1 may be a potential new therapeutic strategy that would be beneficial for more patients with BC or other cancers." (PMID 34249735, 2021). "In addition, the research on NRP1 monoclonal antibodies and cell penetrating peptides highlights it as a promising new target for cancer therapy." (PMID 34298996, 2021). "Similarly, neuropilin-1 levels were significantly higher in patients with grade 3 cancer than in patients with lower grade cancer or controls (p < 0.05)." (PMID 33671851, 2021). "In addition, six tumor suppressor genes previously implicated in cancer (BTK, CHD1, FN1, NFATC2, NOTCH1, and NRP1) were found in at least two samples." (PMID 34489456, 2021). "The association of high level of miR-148a-3p with better prognosis in multiple cancers might be due to repression of NRP1, which promotes cancer cell growth, survival, migration, and angiogenesis within tumors." (PMID 34168096, 2021).
cancer (continued). "Opposite to eye diseases, whereby vascular permeability is considered a valid therapeutic target only when inhibited, a few teams have proposed to exploit NRP1 pro-permeability properties to promote penetration of co-injected anti-cancer drugs and develop more efficient delivery systems." (PMID 33947161, 2021). "Expression level of NRP1 is positively correlated with oncogenic immune cells and genes in cancer tissues in LUSC, suggesting NRP1 might be a pro-tumorigenic factor and potential therapeutic target in LUSC." (PMID 34168096, 2021). "NRP1 is upregulated in Treg cells of cancer patients, suggesting that it may be a novel target of cancer immunotherapy." (PMID 33987449, 2021). "Indeed, the NRP1 signaling pathway is clearly involved in the cancer stem cells maintenance in pediatric tumors, and a significant correlation between NRP1 and CD15 (stem cancer cells marker) has been observed in pediatric tumors database." (PMID 34277411, 2021). "NRP1 protein expression was detected mainly in cancer cells but also in endothelial cells." (PMID 31880322, 2020). "Besides, a negative regulation of p27 by NRP1 has been confirmed, sustaining cancer cell viability in different models." (PMID 32784465, 2020). "Neuropilin-1 is involved in diverse processes, including cancer and angiogenesis." (PMID 32915913, 2020). "Therefore, in this study, we investigated NRP1 mRNA expression and its correlation with prognosis of cancer patients using various databases." (PMID 32408477, 2020). "NRP-1 functions as versatile co-receptors that bind to a number of growth factors and couple with cognate receptor tyrosine kinase signaling pathways involved in cancer progression." (PMID 32801339, 2020). "In conclusion, our data demonstrate that targeting NRP-1 in cancer, using antagonistic anti-NRP-1 Nbs that prevent the interaction with Sema3A, delays growth of CRC tumors and extends the survival through a shift in the MHC-IIhigh/MHC-IIlow ratio and an activation of CRC-specific CD8+ T cells." (PMID 33266104, 2020). "The important role of NRP1 in many malignant tumors has prompted us to study whether NRP1 is a potential therapeutic target for PACA." (PMID 32472711, 2020). "To test whether IDB0076 still had the biological activity, we conducted the HUVEC permeability assay and the NRP1 internalization assay in cancer cells." (PMID 32560565, 2020). "Also, it is an exciting and challenging endeavor to employ NRP1-inhibitory strategies for cancer treatment." (PMID 33014187, 2020). "The role of NRP1 in malignant tumors of human has become a research hotspot in recent years." (PMID 32472711, 2020). "Reports have established that NRP-1 overexpression varies by cancer type." (PMID 32847045, 2020). "Moreover, MC38 cells showed marginal expression of NRP-1, excluding direct effects of Nb1 on cancer cell behavior." (PMID 33266104, 2020). "However, little is known regarding the subcellular transformation of VEGF/NRP1 engagement and its regulation of migrating cancer cells." (PMID 32139668, 2020). "Using a gene-based strategy to ensure the continuous production of Nb1 in the TME, we showed that NRP-1 blockade using Nb1 resulted in a delayed outgrowth of MC38 tumors and consequently enhanced survival, thereby confirming the importance of NRP-1 as a cancer target." (PMID 33266104, 2020). "The importance of NRP1 in regulating EGFR signaling in cancer cells has been described previously." (PMID 32784465, 2020). "The abnormal protein may act on the nucleus, membrane, or cell matrix, thereby leading to the progression of cancer, such as NRP1 protein." (PMID 32849822, 2020). "In conclusion, our data demonstrate that targeting NRP-1 in cancer, using antagonistic anti-NRP-1 Nbs that prevent the interaction with Sema3A, delays growth of CRC tumors and extends survival through a shift in the MHC-IIhigh/MHC-IIlow ratio and an activation of CRC-specific CD8+ T cells." (PMID 33266104, 2020).
cancer (continued). "Disruption of the intra- and extracellular interactions of the VEGF/NRP1 axis or Cdc42 relocation could be performed in clinical practice because it might inhibit cancer cell motility and metastasis." (PMID 32139668, 2020). "Interestingly, an anti-apoptotic response from VEGF/NRP1 signaling has been reported in multiple cell types including cancer cells, stem cells, and neurons." (PMID 33322598, 2020). "In addition, we further analyzed the NRP1 expression among 36 types of cancer and normal tissues from TCGA data." (PMID 32408477, 2020). "Furthermore, deletion of NRP1 inhibits the function of VEGFR in the self-renewal ability of cancer stem cells." (PMID 30871059, 2019). "NRP-1 is over-expressed in cancer and mediates cell survival and metastasis." (PMID 31067776, 2019). "It would also be interesting to determine whether this Nrp-1+PD-1high CD8+ TIL subset is influenced by PD-1 blockade in human cancer samples and to validate Nrp-1 expression on TIL as a predictive biomarker for response to cancer immunotherapy." (PMID 31350404, 2019). "Consequently, several studies have been conducted exploring the potential of NRP-1 for cancer-cell targeted PDT (molPDT) and molVTP." (PMID 33568892, 2019). "O-glycosylation of neuropilin-1 is involved in cancer migration and invasion." (PMID 31420553, 2019). "Aside from the part that NRP-1 plays in physiological processes, it plays many roles in cancer." (PMID 31064153, 2019). "Nrp-1 is a transmembrane glycoprotein that serves as a co-receptor for class III/IV semaphorins, VEGFs, and TGFβ, and is implicated in processes including cell migration, angiogenesis, immunity, and cancer development." (PMID 31681327, 2019). "Besides traditional monoclonals, innovative antigen-specific tools called “nanobodies” have been developed to inhibit NRP1 function, and proven to be effective in sensitizing drug-resistant cancer cells to oncogene-targeted therapies." (PMID 31027288, 2019). "While the inhibition of NRP-1 increased chemosensitivity for different kinds of cancer cells." (PMID 31106153, 2019). "NRP1 is expressed by a variety of cell types; notably endothelial cells and cancer cells." (PMID 31208428, 2019). "Butyrate decreased NRP-1 at mRNA levels and thus recuced its cancer promoting effect." (PMID 31067776, 2019). "Notably, the homologous semaphorin co-receptor NRP1, was successfully targeted in lymphoma cells with an oligopeptidic drug candidate for cancer therapy." (PMID 31143707, 2019). "This Nrp-1+PD-1high CD8+ TIL subset is enriched with CD8+ T cells recognising cancer cells and thus could be used for identifying patients who would respond to antibody combination therapies." (PMID 31350404, 2019). "Taking these findings together, it is tempting to hypothesize that HS3ST3B-modified HS could act by enhancing the interactions between Nrp1, growth factors and their receptors in cancer cells." (PMID 30360368, 2018). "In some cancer patient, NRP1 was upregulated in Treg35,37,40." (PMID 29467366, 2018). "NRP1's role in cancer is increasingly clear, and targeting this co-receptor within the TME, or specifically on GAMs, may prove to be a novel therapeutic strategy." (PMID 30479695, 2018). "The potential prognostic effect of NRP1 expression in cancer has, however, remained unclear." (PMID 30027561, 2018). "Afterward, a proteolytical cleavage takes place to reveal a cryptic RXXK/R motif located at the C-terminus (CendR motif, C-End Rule), which then binds to neuropilin-1 (NRP-1), activating an endocytic transport pathway responsible for the enhanced transport of anti-cancer drugs into tumors." (PMID 29765474, 2018). "Expression of NRP1 in several cancers correlates with cancer stages and poor prognosis." (PMID 29430837, 2018). "Notably, silencing Nrp1 expression in carcinoma cells was shown to impair proliferation, survival and invasion in vitro, while Nrp1 overexpression can inhibit cancer cell apoptosis." (PMID 30360368, 2018).